SMARCA4 (SWI/SNF related BAF chromatin remodeling complex subunit ATPase 4)
Diseases named in the same sentence as SMARCA4 in open-access papers (continued):
Sharing a sentence is not in itself a finding about the gene and the disease.
epithelioid sarcoma (15 papers, 2021 to 2025). An aggressive malignant neoplasm of uncertain differentiation, characterized by the presence of epithelioid cells forming nodular patterns. "Finally, while SMARCB1 deletion is a typical feature of epithelioid sarcoma, the SMARCA4 deletion mutation is only found in SDUS." (PMID 37194064, 2023). "Proximal-type epithelioid sarcoma overlapped with SMARCA4-UT in morphology." (PMID 38347129, 2024). "In the absence of areas of HFLT/PHAT, this lesion would be indistinguishable from rare variants of epithelioid sarcoma or a metastasis from a SMARCA4-deficient malignancy elsewhere." (PMID 34389899, 2022). "In addition, SMARCA4 loss of expression can also be observed in tumors more commonly associated with SMARCB1 loss, such as epithelioid sarcoma." (PMID 33921435, 2021). "In particular, the SWI/SNF subunit SMARCB1 has been approved as an effective marker of metastatic or locally advanced epithelioid sarcoma sensitivity to tazemetostat, while SMARCA2, SMARCA4, ARID1A, and PBRM1 are potential marker candidates." (PMID 34202528, 2021). "A study in head and neck cancer found deletions of SMARCA4 as one of the most common occurrences in patients responding to ICI, and there have been also reports of complete remission in a patient with stage IV SMARCB1-inactivated epithelioid sarcoma." (PMID 39813356, 2025). "The loss of SMARCA4 (BRG-1) can exceptionally occur in tumors such as SMARCB1/INI1-retained epithelioid sarcoma (ES); in this context, the absence of SOX2 and SALL4 expression aids in distinguishing ES from SMARCA4-UT." (PMID 38265099, 2024). "The catalytic ATPase subunit SMARCA2 (BRM) was absent in all lines except VA-ES-BJ (epithelioid sarcoma), while SMARCA4 (BRG1) was detected in all lines except CHLA-06-ATRT (rhabdoid tumour)." (PMID 37236926, 2023).
neuroblastoma (15 papers, 2016 to 2024). Neuroblastoma (NB) is the most common solid, extracranial childhood tumor. "Previous research has shown that loss of SMARCA4 in neuroblastoma does occur and correlates with poor prognosis." (PMID 37664065, 2023). "In vitro and in vivo loss-of-function experiments showed that SMARCA4 is essential for the proliferation of neuroblastoma cells." (PMID 33968920, 2021). "Certain acute leukaemias and small cell lung cancers, which lack SMARC mutations (similar to neuroblastoma) can be vulnerable to inhibition of SMARCA4." (PMID 33968920, 2021). "Tumor suppressor SMARCA4 is usually silenced or mutated in tumors and overexpression of SMARCA4 in neuroblastoma cells diminishes cell viability." (PMID 31137686, 2019). "One was the mother of a 12-year-old child with neuroblastoma found to have a P/LP SMARCA4 variant." (PMID 38138883, 2023). "Here, we show that elevated SMARCA4 expression corresponds strongly to poor outcomes for neuroblastoma patients, whereas elevated expression of SMARCA1 correlates to good outcome, suggesting antagonist roles in neuroblastoma for members of this gene family." (PMID 33968920, 2021). "Conversely, the mRNA and protein expression of one of the catalytic subunits, BRG1 (or SMARCA4), was correlated with advanced stages and poor prognosis in neuroblastoma patients, and this subunit was reported to control an oncogenic transcriptional program in neuroblastoma cells." (PMID 36057593, 2022). "Valproic acid is known to alter the expression of SMARCA4 and SMARCD1 in neuroblastoma cells, and SMARCA genes are suggested as members of the neurogenic transcriptional network control." (PMID 33328862, 2020).
squamous cell carcinoma (15 papers, 2016 to 2025). A carcinoma arising from squamous epithelial cells. "SMARCA4 was detected mainly in the nucleus of squamous carcinoma cells (weak staining in the region of squamous pearl formation) in about 75% of OSCC tissue samples, and normal oral mucosa specimens showed positivity mainly in sporadic cells of basal layers." (PMID 36902184, 2023). "Compared with SMARCA4‐iNSCLC, SMARCA4‐dNSCLC exhibited relatively few squamous cell carcinomas and more poorly differentiated carcinomas (p < 0.05)." (PMID 37184108, 2023). "The pathological types of patients with SMARCA4‐dNSCLC were adenocarcinoma (74%), squamous cell carcinoma (10%), poorly differentiated carcinoma (14%), sarcomatoid carcinoma (1%), and neuroendocrine carcinoma (1%)." (PMID 37184108, 2023). "In an unselected series of NSCLC, loss of SMARCA4 and SMARCA2 was observed all together in 12% of adenocarcinomas (5.5% and 6.4%, respectively) compared to 6.9% (5.2% and 1.7%, respectively) of squamous cell carcinomas." (PMID 33506327, 2021). "They used Western blotting to demonstrate the molecular phenomenon in 30% of NSCLC cell lines and immunohistochemistry to show concomitant loss of SMARCA2 and SMARCA4 in 10% of primary NSCLC tumors across 41 adenocarcinoma and 19 squamous cell carcinoma (SCC) cases." (PMID 39888726, 2025). "Additionally, ARID1A and ARID2 mutations were more frequently found in males, SMARCA4 was more frequently mutated in patients with adenocarcinoma, and the ARID1B mutation was more frequently found in patients with squamous carcinoma, which were all statistically significant." (PMID 34512623, 2021). "SMARCA4-NSCLC typically presents with clear-cut adenocarcinoma (AdCC) features or, less frequently, squamous cell carcinoma (SCC)." (PMID 38265099, 2024). "Histologically, 21 patients (58.3%) were diagnosed with SMARCA4‐NSCLCs, which included 15 NSCLCs not otherwise specified (41.7%), 4 adenocarcinomas (11.1%), 1 squamous cell carcinoma (2.8%) and 1 adenosquamous carcinoma (2.8%)." (PMID 38124509, 2023). "With regards to routine histopathological workup, we identified KRT18 in combination with UCHL1 as potential immunohistochemical markers to differentiate NEC-like IDH2 and NEC-like SMARCA4/ARID1A tumors from adenoid cystic carcinomas, olfactory neuroblastomas and squamous cell carcinomas." (PMID 36443295, 2022). "The NEC-like SMARCA4/ARID1A class (n = 33) mainly consisted of tumors that had been diagnosed as SNUCs, neuroendocrine carcinomas and olfactory neuroblastomas, but also single adenocarcinomas, poorly differentiated carcinomas and squamous cell carcinomas." (PMID 36443295, 2022). "While normal tissue, squamous cell carcinomas and cases from the ACC tumor class were mostly assigned to distinct groups, the differentiation between olfactory neuroblastomas, cases from the NEC-like IDH2 and NEC-like SMARCA4/ARID1A class was less evident." (PMID 36443295, 2022). "Next, n = 116 samples of patients with pure squamous cell carcinoma (n = 68) and mixed urothelial carcinoma with substantial squamous differentiation (n = 48) were analyzed for seven SWI/SNF complex proteins (ARID1A, SMARCA4, SMARCB1, SMARCC1, SMARCC2, SMARCA2 and PBRM1) by immunohistochemistry." (PMID 33227989, 2020). "UCHL1 expression was high in NEC-like IDH2 and NEC-like SMARCA4/ARID1A tumors as well as olfactory neuroblastomas but absent in tumors from the ACC class and squamous cell carcinomas." (PMID 36443295, 2022).
acute myeloid leukemia (14 papers, 2017 to 2025). Acute myeloid leukemia (AML) is a group of neoplasms arising from precursor cells committed to the myeloid cell-line differentiation. "SMARCA2/4 (BRM/BRG) have been widely studied; SMARCA4 is frequently mutated in cancer and maintains oncogenic transcription and cellular proliferation in acute myeloid leukemia (AML)." (PMID 34298819, 2021). "Additionally, we evaluated GeneCompass by in silico deleting more transcription factors (TFs) in various cell types of different species, i.e., STAT1 on human PBMC cells, SMARCA4 on human acute myeloid leukemia cells, CBX8 on mouse embryonic stem cells, and MTA2 on mouse colonic epithelium cells." (PMID 39375485, 2024). "Acute myeloid leukemia (AML) cells were found to be highly sensitive to allosteric SMARCA4/SMARCA2 inhibitors, BRM011 and BRM014." (PMID 38390898, 2024).
lymphoma (14 papers, 2014 to 2025). A malignant (clonal) proliferation of B- lymphocytes or T- lymphocytes which involves the lymph nodes, bone marrow and/or extranodal sites. "An excisional biopsy of the subclavian lymph node led to the diagnosis of malignant lymphoma, which was later corrected to SMARCA4-deficient thoracic sarcoma based on genetic examination." (PMID 32522190, 2020). "The SNF2 genes SMARCA4 (34%), ZRANB3 (32%), and CHD9 (20%) were the three most frequently mutated genes in patients with malignant lymphoma, whereas CHD3 was the most frequently mutated gene in AML." (PMID 25789315, 2015). "However, SMARCA4-UT can mimic other malignancies; with younger-aged patient populations and mediastinum localization, initial diagnosis suspicions are focused on lymphoma and thymic or germ cell tumors." (PMID 38542211, 2024). "Genes frequently mutated in BL are located in the BL-specific spot A (e.g. ID3, CCND3) and D (e.g. TCF3, SMARCA4, MYC) indicating their increased activity in BL and partly in intermediate lymphomas." (PMID 31039827, 2019).
bladder cancer (13 papers, 2014 to 2025). "This effort also led to the identification of the developmental origin of this SMARCA4‐deficient undifferentiated tumor as a non‐invasive bladder cancer." (PMID 38923369, 2024). "In this study, we report a case of a SMARCA4‐deficient undifferentiated urothelial carcinoma with high PD‐L1 expression that was effectively treated with nivolumab after early relapse following treatment for non‐invasive bladder cancer." (PMID 38923369, 2024). "In this study, we report a case of a SMARCA4‐deficient undifferentiated urothelial carcinoma that was effectively treated with nivolumab (Nivo; anti‐programmed cell death protein [PD‐1] blockade) after early relapse following treatment for non‐invasive bladder cancer." (PMID 38923369, 2024). "SMARCA4 R1189Q has been reported in 2 COSMIC samples, and in GENIE, 3 of 7 samples were bladder cancer." (PMID 30709382, 2019).
heart failure (13 papers, 2013 to 2025). Inability of the heart to pump blood at an adequate rate to meet tissue metabolic requirements. "As in rodents, expression of MSK1/2, IEG components of the AP-1 complex and SMARCA4 were substantially upregulated in heart failure CM." (PMID 35203255, 2022).
liver cancer (13 papers, 2017 to 2025). An epithelial or non-epithelial malignant neoplasm that arises from the liver. "This highlights the therapeutic potential of targeting the ceRNA network involving GAS5, miR-423-3p and SMARCA4 in liver cancer." (PMID 40451925, 2025). "qRT–PCR and western blot analyses of liver tissues confirmed a direct correlation between reduced Gas5 and Smarca4 expression and liver cancer prophylaxis." (PMID 40451925, 2025). "Kaplan–Meier survival curve analysis suggested that the overall survival of liver cancer patients with high SMARCA4 expression was shorter than that of patients with low SMARCA4 expression." (PMID 34083693, 2021). "We next investigated whether inhibiting the oncogenic sponge effect involving GAS5, miR-423-3p and SMARCA4 could serve as a potential strategy for liver cancer intervention." (PMID 40451925, 2025). "Divergent lncRNA of FZD6 (lncFZD6) recruits the BRG1 (Brahma-related gene 1; SMARCA4)-embedded SWI/SNF complex to the FZD6 promoter, driving the FZD6 transcription in liver cancer." (PMID 32429086, 2020).
neuroendocrine carcinoma (13 papers, 2009 to 2025). A malignant neuroendocrine neoplasm composed of cells containing secretory granules that stain positive for NSE and chromogranin. "The second most frequently mutated gene in TCS is CTNNB1, encoding β-catenin and frequently co-occurring with SMARCA4 mutations in TCS and in SMARCA4-deficient carcinoma, olfactory carcinoma and neuroendocrine carcinomas." (PMID 38201285, 2023). "SMARCA4 deficiency can be present in TTF-1-negative neuroendocrine carcinomas." (PMID 38090508, 2023). "SMARCA4 mutations have been reported in a few neuroendocrine carcinomas." (PMID 38090508, 2023). "Melanoma, mesothelioma, small cell carcinoma, large cell carcinoma, malignant rhabdoid tumor, neuroendocrine carcinoma, and small cell carcinoma of the ovary, hypercalcemic type (SCCOHT), can also present with SMARCA4 deficiency." (PMID 40421964, 2025). "Evaluation of the neuroendocrine markers in thoracic SMARCA4-dUT is relevant considering the differential diagnosis including neuroendocrine carcinoma, which has high mitotic activity and necrosis, similar to thoracic SMARCA4-dUT." (PMID 40909976, 2025). "Mutations in CDKN2A or RB1 co-occurring with SMARCA4 or ARID1A have been reported previously in olfactory neuroblastoma and neuroendocrine carcinoma." (PMID 38201285, 2023). "Concomitant mutations in two or more SWI/SNF genes have not been described in TCS to date, but do occur in SMARCA4-deficient carcinoma, olfactory carcinoma and neuroendocrine carcinomas —tumors that with TCS may be regarded as different morphotypes of one tumor entity." (PMID 38201285, 2023). "Other differentials include neuroendocrine carcinoma, large cell lymphoma, germ cell tumors, thymic carcinoma, and NUT carcinoma, which can be ruled out by positive SMARCA4 staining." (PMID 40421964, 2025).
BAFopathies (12 papers, 2020 to 2024). "Notably, PTHS exhibited the highest percent of DMPs overlapping with BRG1/BRM-associated factor (BAFopathy) (4%, including ARID1A, ARID1B, SMARCB1, SMARCA2, and SMARCA4) and coloboma, heart anomaly, choanal atresia, retardation, genital and ear anomalies (CHARGE) (4%, CHD7)." (PMID 38571311, 2024). "For example, such intricate interplay becomes evident in the episignature associated with TRIP12, which exhibits partial overlap of DMPs included in the signature linked to BAFopathies (ARID1B; ARID1A; SMARCB1; SMARCA4; SMARCA2)." (PMID 39135741, 2024). "Studies have shown that DNAm profiles at subsets of CpGs overlap between individuals with BAFopathies carrying variants in SMARCA2 that cause NCBRS, and in ARID1B, SMARCB1, and SMARCA4 that lead to Coffin-Siris syndromes type 1, 3, and 4, respectively." (PMID 35361921, 2022). "Typical CSS, which is also referred to as BAFopathy, is caused by variants in the subunit of BAF complex, including ARID1A (OMIM#603024), ARID1B (OMIM#614556), SMARCA4 (OMIM#603254), SMARCB1 (OMIM#601607), ARID2 (OMIM#609539), and SMARCE1 (OMIM#603111)." (PMID 35938035, 2022). "BAFopathy presented with a ~4% overlap, including ARID1A, ARID1B, SMARCB1, SMARCA2, and SMARCA4, and includes several neurodevelopmental disorders caused by variants in genes within the BRG1/BRM-associated factor (BAF) complex." (PMID 37762546, 2023). "Among the most prominent and most studied BAFopathies are the clinically overlapping syndromes CSS and Nicolaides-Baraitser (NCBRS) (MIM: 601358), caused by variants in BAF complex proteins: ARID1B in CSS1, SMARCB1 in CSS2, and SMARCA4 in CSS4; and SMARCA2 in NCBRS." (PMID 38751117, 2024). "We detected a predominantly hypermethylation profile; the highest percentage of overlap in DMPs was with BAFopathies (11%, including ARID1A, ARID1B, SMARCB1, SMARCA2, SMARCA4), and CHARGE syndrome (10%, CHD7)." (PMID 38351292, 2024). "Other combined episignatures, such as for the BAFopathy (genes: ARID1A, ARID1B, SMARCB1, SMARCA2 and SMARCA4) episignature, are already proving their clinical utility." (PMID 38787418, 2024). "This analysis showed that TRIP12 is most closely related to the CSS9 (SOX11), BAFopathy (ARID1A, ARID1B, SMARCB1, SMARCA2, SMARCA4) and MRD23 (SETD5) episignatures." (PMID 36430143, 2022). "Notably, JARID2 exhibited the highest overlap with CHARGE (~7%, CHD7), BAFopathy (~4%, including ARID1A, ARID1B, SMARCB1, SMARCA2, SMARCA4), and the PCR2 complex, which houses Cohen–Gibson syndrome (COGIS) and Weaver syndrome (WVS) (~4%, EED, EZH2)." (PMID 37762546, 2023).
small cell lung carcinoma (12 papers, 2009 to 2026). Small cell lung cancer (SCLC) is a highly aggressive malignant neoplasm, accounting for 10-15% of lung cancer cases, characterized byrapid growth, and early metastasis. "In a subgroup of 239 small cell lung cancer (SCLC) patients across four studies, comprising 249 samples, the SMARCA4 mutation rate was only 2.9%." (PMID 41577374, 2026). "Recently, Romero and colleagues found another putative synthetic lethality that also involves SMARCA4 and that could be exploited as a putative therapy in small cell lung cancer (SCLC)." (PMID 25391308, 2014). "However, there are no reports of fatality in SMARCA4-deficient small-cell lung carcinoma (SCLC) with hyper-progressive disease (HPD) upon treatment with ICIs." (PMID 32995013, 2020).
atherosclerosis (11 papers, 2014 to 2025). A disease characterized by the build-up of fatty material and calcium deposition in the arterial wall resulting in partial or complete occlusion of the arterial lumen. "It has been suggested that macrophage-derived EVs containing mir-199a-5p inhibit the expression of SMARCA4, thereby reducing endothelial cell apoptosis and alleviating atherosclerosis." (PMID 38493291, 2024). "The strongest association signal (index SNP: rs1122608, Pmeta = 2.23 × 10–13) was found near gene SMARCA4 on chromosome 19, which was previously reported to regulate atherosclerosis and play a protective role to against the risk of HTN." (PMID 36187959, 2022).
brain tumors (11 papers, 2020 to 2025). "The role SMARCA4 plays in tumourigenesis is highly variable and largely dependent on the type of brain tumour, with the SMARCA4 mutational landscape across brain tumours being diverse." (PMID 37433987, 2023). "The chromatin remodeler SMARCA4/BRG1 is a key epigenetic regulator with diverse roles in coordinating the molecular programs that underlie brain tumour development." (PMID 37433987, 2023). "Atypical teratoid/rhabdoid tumor (AT/RT) is a highly malignant brain tumor in infants that is characterized by loss of nuclear expression of SMARCB1 or SMARCA4 proteins." (PMID 36127323, 2022). "This potential aberrant NPC specification could be a contributing factor to the aggressiveness and poor prognoses of SMARCA4-mutated brain tumors." (PMID 38427725, 2024). "SMARCA4 and other BAF subunit gene mutations have been identified in multiple aggressive pediatric brain tumors." (PMID 38427725, 2024). "However, SMARCA4 is opposingly seen to promote tumourigenesis in the absence of mutation and through overexpression in other brain tumours." (PMID 37433987, 2023). "Definition of ATRT: ATRTs are embryonal brain tumors histologically characterized by cells with rhabdoid features and molecularly characterized by biallelic inactivation of SMARCB1 or SMARCA4." (PMID 33415075, 2020).
atypical teratoid rhabdoid tumor (10 papers, 2021 to 2025). Atypical teratoid rhabdoid tumor (ATRT) is a highly malignant central nervous system (CNS) rhabdoid tumor (RT) found almost exclusively in children. "Although SMARCA4 mutations are less penetrant for atypical teratoid rhabdoid tumor than SMARCB1, SCCOHT was exclusively observed in patients constitutionally carrying the deleterious variant of SMARCA4." (PMID 33907931, 2021). "Atypical Teratoid Rhabdoid Tumor (ATRT) is an embryonal CNS tumor of early childhood with a poor prognosis, characterized by biallelic inactivation of SMARCB1 (or, less commonly, SMARCA4), a core component of the SWI/SNF chromatin remodeling complex." (PMID 41408661, 2025).
Burkitt lymphoma (10 papers, 2016 to 2024). A rare form of malignant mature B-cell non-Hodgkin lymphoma. "Interestingly, FAT1 has been reported in resistance in CLL and SMARCA4 was associated with Burkitt lymphoma." (PMID 27285986, 2016).